CD81 (CD81 molecule)
Diseases named in the same sentence as CD81 in open-access papers (continued):
Sharing a sentence is not in itself a finding about the gene and the disease.
melanoma (continued). "We also performed RT-PCR and western blotting to verify the diagnostic applicability of the isolated EVs, and detected mRNA derived from melanoma cells and CD81 in isolated EVs." (PMID 26090684, 2015). "In line with this, α-syn and CD81 have been hypothesized to concertedly play an immunosuppressive role in the melanoma tumor microenvironment, potentially leading to enhanced melanoma aggressiveness and decreased patient survival." (PMID 41460324, 2025). "Using an ASO might be better than targeting L1CAM and CD81 with antibodies, as two monoclonal antibodies would have to be used, which would likely be toxic to melanoma patients." (PMID 40521809, 2025). "Overall, these results highlight how α-syn can affect the aggressiveness of melanoma and its evolution, not only by enhancing cellular motility through the transport and trafficking of CD81, L1CAM, and N-cadherin but also by shaping the immune landscape of the tumor microenvironment." (PMID 41460324, 2025). "Bead-based multiplex analysis revealed the robust expression of the sEV tetraspanins CD9, CD63, and CD81 in addition to CD29 (Integrin beta- 1), the MSC-EV-specific markers CD44 (hyaluronic acid receptor) and MSCP/NG2 (melanoma‐ associated chondroitin sulfate proteoglycan)." (PMID 38764077, 2024). "Interestingly, overexpression of CD81 in a human melanoma cell line upregulated MT1-MMP expression and activity with a consequent increased invasion and metastases in vitro and in vivo." (PMID 29946318, 2018). "Similarly, upregulated CD81 expression in melanoma was found to contribute to an enhanced metastatic phenotype." (PMID 29946318, 2018). "Data show that CD81 and SR-B1 are present in exosomes from patients diagnosed with melanoma." (PMID 26964503, 2016). "In addition, MICA+ EVs from this melanoma cell line contained more CD81 than CD9." (PMID 36726591, 2022). "Interestingly, a series of specific proteins have been detected in the CD81-positive small extracellular vesicles through proteomics in melanoma, strengthening the circulating sEV as a systematic biomarker for early diagnosis for melanoma patients." (PMID 36338621, 2022). "The 10% of human CD81 positivity detected in sEVs purified from the mouse plasma suggests that this could be the fraction of human sEVs released in the mouse bloodstream by the melanoma tumor cells in the brain." (PMID 32575666, 2020). "These EVs were enriched with vesicular marker proteins (CD9, CD81 and Tsg101), tyrosinase, F4/80, alpha-smooth muscle actin and E-selectin, suggesting that melanoma cell-, macrophage-, fibroblast- and endothelial cell-derived EVs are present in the melanoma microenvironment." (PMID 26082317, 2013). "Oleic acid (C18:1), the most abundant unsaturated FA in lipid membranes, was also significantly elevated in CD81 sEVs of stage II and III–IV melanoma." (PMID 40111100, 2025). "PEVs also influenced the melanoma spheroids’ own EV production by modifying their tetraspanin (CD63, CD9, and CD81) profiles." (PMID 39695652, 2024). "In the A2058 spheroids, CRP PEVs significantly increased CD81- and decreased CD9-containing melanoma EV formation, whereas FFV PEVs increased the formation of CD63- and CD81-containing melanoma EVs." (PMID 39695652, 2024). "The identification of all the exosomes derived from all three melanoma cell lines was further confirmed by the exosomal markers CD63, CD9, and CD81 using immunoblotting." (PMID 39123364, 2024). "Overexpression of CD81 partially rescued the infertility phenotype seen in CD9 KO mice and it was recently demonstrated that CD9 deletion in human melanoma cells was quickly compensated by CD63 expression upregulation." (PMID 34847198, 2021). "In early stage melanoma cells, when TGFβ signaling is low, EWI-2 is strongly expressed and interacts with CD9 and CD81, thereby sequestering CD9 and CD81 from the TGFβ receptor complex." (PMID 32274581, 2020).
melanoma (continued). "In melanoma cells with elevated expression of α-syn, there is robust anterograde membrane traffic that results in the delivery of key adhesion molecules, which control invasion and migration, to the plasma membrane, i.e. L1CAM and CD81 and others." (PMID 40521809, 2025). "We investigated whether the fatty acid (FA) and protein compositions of small extracellular vesicles (sEV) expressing CD81, derived from the plasma of stage 0–I, II and III–IV melanoma patients, could reflect disease stage." (PMID 34439311, 2021). "Several other tetraspanins, mainly CD9, CD81, CD82 and CD151 have been described to regulate proMMP-2 and/or proMMP-9 expression in cancer cell lines from liver, kidney, breast and lung carcinomas, fibrosarcomas and melanomas." (PMID 32455575, 2020). "CD81 interacts with CD9 (another member of the tetraspanin family), which is also significantly upregulated in TCam-2 cells (supplementary ), and both play an important role in the TGF beta signaling pathway in melanoma cells." (PMID 31565104, 2019). "Among the proteins that were found in MVs as well as both exosome subpopulations isolated from melanoma cells, we found suggested EV and exosome marker proteins ALIX, TSG101, CD9, CD81 and CD63, however their relative abundance was higher in LD-Exo and HD-Exo as compared to MVs." (PMID 26931825, 2016). "We detected CD42a on platelet EVs while CD81 was lacking and, thus, considered an elevated proportion of platelet EVs in melanoma plasma." (PMID 27507971, 2016). "Also, we identified that melanoma-derived LEVs may be more enriched with CD9, CD63 and CD81 than nevi-derived EVs." (PMID 41268555, 2025). "Transfection of CD81 into melanoma cells lacking endogenous CD81 expression could significantly enhance the migrating, invasion, and metastatic abilities of melanoma cells." (PMID 35705919, 2022). "However, it was established that the cell surface protein EWI-2 negatively regulated TGF-β signaling in melanoma by sequestering CD9 (and CD81) and thereby impeding complex formation between TGFβ receptor 1 (TβR1) and TGFβ receptor 2 (TβR2), leading to diminished TGF-β signaling." (PMID 33424923, 2020). "However, in later stage melanoma cells when TGFβ signaling is high, EWI-2 is downregulated, which allows its two tetraspanin partners CD9 and CD81 to engage with TGFβ receptors and stabilize a signaling active TGFβ receptor complex resulting in increased Smad signaling." (PMID 32274581, 2020). "The detection of GFP+/Rh+ and CD63+/GFP+ events in A375 melanoma cells expressing GFP-SR-B1, but not CD81+/GFP+ events, suggests that GFP modification of SR-B1 may prevent GFP-SR-B1 sorting to CD81+ exosomes." (PMID 26964503, 2016). "Notably, CD81 and CD9-positive vesicles derived from melanoma Mel501 cells, although not very abundant, exhibited a high level of protein expression (MFI) on single Bodipy-exo, indicating that the vesicles, although not very represented, are enriched in these tetraspanins." (PMID 40643510, 2025).
viral infection (28 papers, 2007 to 2025). "A clear correlation between the CD81 expression levels and susceptibility to WT virus infection was observed in them." (PMID 19088272, 2009). "A polyclonal antibody against CD81 LEL domain significantly blocks the virus infection in the cells." (PMID 39745447, 2025). "In this context, CD81 is known to facilitate cells adhesion or fusion in the frame of viral infection." (PMID 37046846, 2023). "CD81 KO cell lines provide a convenient system to appreciate the role of tetraspanin in various situations, notably to study virus infection and cancer cell aggressivity." (PMID 37046846, 2023). "CD81 is also involved in virus infection and is related to HIV-1 and hepatitis C virus (HCV) infection." (PMID 34824296, 2021). "On the contrary, very little core signals were detected in viral infections that were treated with DHMD or anti-CD81, suggesting that both treatments effectively blocked the earlier HCV particle binding onto the hepatoma cells." (PMID 27426693, 2016). "When HLCZ01 cells were treated with anti-CD81 antibody before viral inoculation, viral infection efficiency was markedly decreased." (PMID 24727952, 2014). "Secondly, blocking viral infection with anti-CD81 antibody markedly decreased virus-induced apoptosis." (PMID 24727952, 2014). "We found that CD81 primarily affected virus infection at two stages: viral uncoating during entry and virus budding." (PMID 24130495, 2013). "We found that CD81 plays functional roles in two separate steps of viral infection: viral fusion and virus budding." (PMID 24130495, 2013). "Upon dissecting each of the major steps in influenza infection pathway, we found that CD81 was required for productive viral infection and that CD81 primarily functions at two stages: viral fusion within endosomes and virus budding." (PMID 24130495, 2013). "CD81 has been shown to function as a pivotal role in both cell-free virus infection and cell-to-cell viral transmission." (PMID 23349980, 2013). "In the subsequent experiments, we aimed to determine which post-entry step(s) of the viral infection process are CD81 dependent." (PMID 24130495, 2013). "HepG2 cells expressing T149A, E152A or T153A CD81 mutants showed minimal evidence for HCVpp infection, whereas cells expressing K148A or K148A/T149A CD81 supported virus infection at comparable levels to WT CD81." (PMID 22897233, 2012). "When PHH were treated with anti-CD81 antibody before viral inoculation, viral infection efficiency was markedly decreased in a dose-dependent manner." (PMID 22087337, 2011). "However, studying the biogenic proteins of exosomes in viral infections is crucial because tetraspanins, such as CD81, CD63, and CD9, are involved in viral release and regulate the increase in exosome production." (PMID 40572291, 2025). "The key roles played by CD81 in oncology and in other therapeutic areas, notably in the fields of viral infection and inflammation, has increased interest for the discovery of molecules, large and small, binding to CD81 and/or capable of neutralizing its effects." (PMID 37046846, 2023). "Therefore, we need to consider the regulation of CD81 transcription by transcription factors other than Pax5 under special conditions, such as cytokine stimuli, stress responses, viral infection, and B-cell developmental stages." (PMID 34824296, 2021). "CD81 is involved not only in viral infection, but also in cell biological processes." (PMID 32322956, 2020). "To determine the impact of exogenous exosomes (human plasma, breast milk, and HEK 293) on HIV-1 entry and subsequent gene expression, we performed a series of viral infection experiments using exosomes only, virus only, exosomes with virus, or exosomes with virus and anti-CD81 antibody." (PMID 29429034, 2018). "We note that there was only a modest decrease of CD81 expression upon viral infection." (PMID 24130495, 2013).
viral infection (continued). "Because CD81-knockdown cells reduced viral infection and exhibited a higher reduction in virus titer when infected without acid bypass than when infected with acid bypass, viral fusion within CD81+ endosomes likely leads to productive influenza infection." (PMID 24130495, 2013). "Blocking viral infection with anti-CD81 antibody markedly reduced apoptosis of viral infected PHH." (PMID 22087337, 2011). "Both the HCVpp and HCVcc systems support a crucial role for CD81 in mediating virus infection." (PMID 19088272, 2009). "For example, overexpression of IFI6-16 inhibited genome replication and gene expression of HBV (hepatitis B virus) in HepG2 cells, and researchers also found that IFI6-16 could inhibit HCV (hepatitis C virus) infection by impairing EGFR mediated CD81 co-localization with claudin-1." (PMID 35632802, 2022). "Antibodies against CD81 or recombinant CD81-LEL proteins can inhibit HCV pseudoparticles and HCV cell culture-derived virus infections (48, –, 50)." (PMID 39745447, 2025). "Meanwhile, CD81 as a central regulator in the infection of human hepatocytes by HCV, has been shown to augment the levels of activated Rho GTPases during the viral infection process, thereby facilitating HCV infection." (PMID 39745447, 2025). "Taken together, these data indicate that HCV-Exo mediate a CD81-, SR-BI- and ApoE receptor-independent effect on MDSC induction during viral infection." (PMID 30210805, 2018). "CD81 is a critical component of HCV receptor, so we blocked viral infection using the antibody against human CD81." (PMID 22087337, 2011). "CD81, CD63, and CD9 signals on CSF EVPs were significantly decreased in the viral disease group (p = 0.005, p = 0.0151, and p = 0.0050, respectively) compared to the non-viral disease group, although this trend is likely heavily influenced by the HAM patient CSF EVPs (open blue circles)." (PMID 37622115, 2023). "It is known that CD81 participates, in concert with other tetraspanins, like CD63 and CD9, in many biological processes such as cell adhesion, migration, cell–cell fusion as well as in multiple steps of viral infection, especially in the case of HIV-1." (PMID 36988579, 2023). "Although the exact role of CD81 in the course of virus infection is not well defined, it is a key molecule required for productive infection by HCVpp and HCVcc of Huh-7 cells." (PMID 18382656, 2008). "Another example of tetraspan molecule promoting viral entry is CD82 and CD81 molecules in case of HTLV-1 virus, however in this case, binding of CD81 to viral glycoprotein E2 does not correlate with permissiveness of cells to virus infection." (PMID 17572908, 2007). "No doubt, CD81 is a target of interest and CD81-interacting drugs could be exploited in various therapeutic domains, not limited to oncology and viral diseases." (PMID 37046846, 2023). "In future studies, if larger serum/plasma volumes are available, we plan to perform flow cytometry studies to investigate whether or not viral infection alters the proportion of exosomes that care Contactin-2 Tag-1 and/or CD-81." (PMID 40012720, 2021). "CPE could be blocked by antibodies to CD81, by anti-HCV-specific immunoglobulins and by anti-E2 monoclonal antibodies, confirming the link between cell death and viral infection." (PMID 20502631, 2010). "Huh7.5.1-8 cells were permissive to both HCV-JFH1-tau and HCV-JFH1-tau Lot B1 infection, and 751r cells were non-permissive to both virus infections, suggesting that HCV-JFH1 Lot B1 infection depends on CD81." (PMID 36424447, 2022).
lung carcinoma (20 papers, 2013 to 2025). "This study applied SPR and QCM-D to studythe concentration of EVs using three well-defined tetraspanin biomarkers(CD9, CD63, and CD81) in lung cancer cells." (PMID 37307147, 2023). "As a member of the tetraspanins family, CD81 play a central role in organizing endosomal membranes for assisting viral fusion while infecting A549 lung carcinoma cells." (PMID 35317717, 2022). "Exosomes derived from lung cancer cells had typical exosome markers, such as CD81, TSG101 and calnexin, which fits with the previously reported protein content for exosomes." (PMID 31664930, 2019). "Interestingly, Linc01703 does not directly impact the proliferation and invasion capabilities of lung cancer cells but rather inhibits cancer metastasis by promoting the secretion of CD81+ exosomes through the Rab27a/SYTL1/CD81 transport complexes." (PMID 38136327, 2023). "Importantly, our analysis of lung cancer tissues revealed a correlation between reduced CD81 expression and an unfavorable patient prognosis." (PMID 38136327, 2023). "For instance, based on the soft clustering method and nested comparisons, we found that MUC5B and SELL have potential diagnostic values for lung cancer cases of BM, and the best accuracy was achieved when separating cases of BM and LA from LM using the combination of APOH, CD81, and CCT5." (PMID 37770976, 2023). "Additionally, we observed decreased CD81 in lung cancer tissues, which correlates with a poor prognosis in patients." (PMID 38136327, 2023). "In subsequent experiments, we used siRNA 1 to deplete CD81 in A549 lung carcinoma cells." (PMID 24130495, 2013). "However, it remains unclear whether CD81 is transmitted to target cells through exosomes and then exerts tumor-promoting or tumor-inhibiting effects in lung cancer." (PMID 38136327, 2023). "Furthermore, EVs isolated with anti-CD61 beads enclosed mRNA expression patterns that might be associated to early-stage lung cancer, in contrast with EVs captured through CD9, CD63 or CD81." (PMID 35933395, 2022). "Ten patients with stage II–IV lung cancer were given D-fraction therapy in human research, and the number of CD41 and CD81 cells, NK cell activity, and serum levels of sIL-2R were then tracked." (PMID 40142097, 2025). "In accordance with the Minimal Information for Studies of EVs 2024 (MISEV), several known EV markers, including CD9, CD81, Flotillin-1, and TSG101, were observed in the purified serum EVs of patients with lung cancer and healthy individuals." (PMID 41007624, 2025). "Specifically, we showed that lung cancer cells release exosomes with typical exosome markers, such as TSG101, CD81 and calnexin." (PMID 31664930, 2019). "CD9 and CD81 are KLF4 transcriptional targets, regulating KLF4-CD9/CD81-JNK signaling pathway and TGFβ1/SMAD signaling pathway, indicated some KLFs via different mechanisms play important roles in inhibiting the growth of lung cancer." (PMID 38560274, 2024). "In any case, cancer patients presented, in general, higher CD63+-CD81+ signal than non-cancer donors, in line with previous observations in lung cancer patients compared with healthy donor plasma." (PMID 36726591, 2022). "By applying targeted mass spectrometry with stable isotope-labeled peptide standards, we assessed the levels of 28 EV-associated proteins, including the conventional exosome markers CD9, CD63, CD81, CD82, and HSPA8, in vesicles derived from the lung cancer cell lines NCI-H23 and A549." (PMID 34684727, 2021).